GSTP1P1 (glutathione S-transferase pi 1 pseudogene 1)
Synonyms: GSTP1P; Lnc712; formerly GST3L; GSTPL; GSTPP
Gene: Processed pseudogene on chromosome 12 (55,900,300 to 55,900,618, forward strand). Ensembl gene ENSG00000257569.
Diseases named in the same sentence as GSTP1P1 in open-access papers:
GSTP1P1 is named in the same sentence as 3 diseases in open-access papers, as found by Europe PMC text mining. Sharing a sentence is not in itself a finding about the gene and the disease.
GSTP1P1 shares sentences with these, for which no sentence is quoted: tumor (2 papers); breast carcinoma (1); cancer (1).